INS (insulin)
Diseases named in the same sentence as INS in open-access papers (continued):
Sharing a sentence is not in itself a finding about the gene and the disease.
insulin-resistant diabetes (33 papers, 2015 to 2025). "These relatively low levels reflect the impoverished insulin secretion of long-standing insulin resistant diabetes and are associated with high-dose exogenous insulin, glucotoxicity, and β-cell failure." (PMID 26222846, 2015). "In this study, we show that the expression of trbl mediated by the ppl-Gal4 driver, a tool commonly used to drive the expression of transcripts in the fat body of flies, leads to a reduction in insulin signalling, reminiscent of phenotypes associated with insulin-resistant diabetes in mammals." (PMID 37083954, 2023). "Metformin (1,1‐dimethylbiguanide) is the first line of therapy in insulin‐resistant diabetes due to its ability to prevent hepatic gluconeogenesis, increase peripheral glucose uptake, and improve insulin sensitivity." (PMID 38798180, 2024). "That perspective arose from familial studies of insulin-resistant diabetes, which established that GSK3β is required for insulin signal transduction." (PMID 37895969, 2023). "This role of GSK-3 in the insulin signaling pathway provides a mechanistic approach to the use of GSK-3 inhibitors in the treatment of insulin-resistant diabetes." (PMID 36627919, 2023). "In severely insulin-resistant diabetes plasma insulin concentrations are usually extremely high, and therapy with insulin-sensitising agents is strongly favoured over secretagogues such as sulfonylureas." (PMID 35618782, 2022). "Neu3 preferentially hydrolyses gangliosides and is involved in insulin signalling and insulin-resistant diabetes mellitus." (PMID 32251344, 2020). "Conversely, cluster 2, labeled as severe insulin-resistant diabetes (SIRD), including 9 (3%) patients, was characterized by either high insulin secretion or resistance." (PMID 41003147, 2025). "For instance, a recent study reported on insulin‐resistant diabetes in RMS, which is relatively unresponsive to first‐line antidiabetic treatments, including metformin and insulin." (PMID 41424588, 2025).
myopia (33 papers, 2008 to 2026). "Conversely, diets high in refined carbohydrates are associated with an elevated risk of myopia, likely due to insulin-mediated mechanisms influencing scleral structure." (PMID 42194741, 2026). "Elevated insulin levels can enhance the growth-promoting effects on ocular tissues, potentially accelerating eye elongation and increasing the risk of myopia." (PMID 40933557, 2025). "Another factor associated with myopia is consumption of refined carbohydrates, where prolonged high sugar intake has a significant effect on the body’s serum glucose and insulin levels." (PMID 38076237, 2023). "Our study found that higher insulin levels were associated with myopia, especially in male adolescents." (PMID 38076237, 2023). "Several studies have identified an association between metabolic control of glucose (insulin/glucagon pathways) and myopia in humans." (PMID 35262731, 2022). "Further studies have proposed that a certain concentration of exogenous insulin can also act on the eyes of form-deprivation animal models, causing a further deepening of myopia and an increase in the length of the eye axis." (PMID 34001063, 2021). "The exact mechanism underlying the link between obesity and myopia remains unclear, but insulin resistance has emerged as a significant factor." (PMID 39408299, 2024). "–202 Interestingly, insulin and glucagon show opposing effects on eye growth in chickens, with glucagon mostly increasing choroidal thickness (associated with myopia inhibition) and insulin mostly increasing ocular elongation, proposed to be controlled by glucagon-positive amacrine cells." (PMID 35262731, 2022). "Future studies exploring the effect of common variants annotated to GJD2(Cx36) on insulin/glucagon levels and the subsequent potential impact on myopia development may help to elucidate this potential mechanism." (PMID 35262731, 2022). "As insulin is a strong stimulator of axial myopia in chicks, elevated PAX6 expression may increase the risk of developing myopia through increased expression of insulin." (PMID 19907666, 2009). "However, only serum insulin level was found to be associated with myopia." (PMID 36229775, 2022). "H3K18la activates the expression of Notch1 in the insulin signalling pathway, thereby forming a ‘glycolysis—H3K18la—Notch1’ axis that induces myopia." (PMID 40984037, 2025). "Insulin and insulin-like growth factor-1 (IGF-1) are implicated in both myopia progression and MetS, providing a potential biological basis for their association." (PMID 40076793, 2025). "This pathway, activated by stimuli such as insulin, impacts retinal pigment epithelial cells’ proliferation, which is essential for pathological myopia." (PMID 40933557, 2025). "Longitudinal studies tracking glycemic control, insulin levels, and myopia progression in diabetic patients can provide valuable data on effective management strategies." (PMID 40933557, 2025). "These multiple pathways interaction suggests that insulin plays a significant role in eye development and can influence the elongation of the eyeball, contributing to myopia." (PMID 40933557, 2025). "The study suggests that reducing near work within 1 h after meals can prevent elevated insulin and scleral hypoxia that induce myopia." (PMID 40984037, 2025). "Insulin affects both the elongation of the eye and the thickness of the choroid to modulate myopia development." (PMID 38684840, 2024). "Subgroup analysis was performed according to insulin measurement and found that the trend of myopia deepening with increasing insulin levels remained robust, especially in male individuals, but there were some differences in the effect between races." (PMID 38076237, 2023). "In the multivariate regression model, as insulin levels increased, there was a shift towards myopia in refractive status (β = −0.013, 95% CI: −0.023 to −0.004)." (PMID 38076237, 2023).
myopia (continued). "Evidence from animal models also supports the possible mechanism through which high insulin levels can trigger myopia." (PMID 36593443, 2023). "This network was composed primarily of genes involved in immune-mediated ECM remodeling, and included connections with many intermediate genes that have been strongly linked to myopia in previous targeted studies (e.g. MMP2, TGFB1, TGFB2, FGF2, INS, and IGF2)." (PMID 28852117, 2017). "The PI3K–Akt pathway was also reported to be activated in plus lens-treated myopia while a PI3K inhibitor attenuated the effects of insulin in minus lens-treated myopia in chicks." (PMID 24810957, 2014). "The group that developed the highest amount of myopia (insulin plus MEK inhibitor injection) also had the longest axial length, the deepest anterior chamber, and the thickest lens." (PMID 23112573, 2012). "Intravitreal insulin has been shown to be a powerful stimulator of myopia in chickens, in particular if the retinal image is degraded or defocused." (PMID 23112573, 2012). "The highest axial length in the eyes injected with insulin plus U0126 correlated with the highest amount of myopia measured in this group." (PMID 23112573, 2012). "In agreement with previous studies, insulin induced not only myopia but also overcompensation of the power of the lenses in animals wearing negative lenses." (PMID 23112573, 2012). "Additionally, shared biological pathways, including vascular inflammation and insulin signaling, connect the pathogenesis of myopia with obesity, diabetes, and MetS." (PMID 40076793, 2025). "In addition, Li reported that PI3K/AKT/mTOR signaling participates in the insulin-mediated regulation of pathological myopia-related factors in retinal pigment epithelial cells." (PMID 40216914, 2025). "The present cross-sectional study demonstrated that higher insulin levels may promote the development of myopia in adolescents, but there may be variations across gender and ethnicity." (PMID 38076237, 2023). "Recent studies have suggested that insulin resistance may contribute to the ocular axial length, which in turn results in myopia." (PMID 35333875, 2022). "In addition, insulin has been found to promote myopia development both in vitro and in vivo studies." (PMID 35652067, 2022). "The present study analyzed the effect of insulin intravitreal injections on the activation of the PI3K/Akt or MEK/ERK signaling cascades as a possible mechanism responsible for eye growth in the chicken model of myopia." (PMID 23112573, 2012). "Although Pax6 also transactivates the glucagon promoter, which is a “stop” for myopia, insulin might overcome the effects of glucagon in the development of myopia." (PMID 19907666, 2009). "Further analysis using an insulin microarray resulted that the levels of insulin and those related factors including IGF2, IGF-2R, IGF binding protein 1 (IGFBP-1), IGFBP-2, IGFBP-3, IGFBP-4 and IGFBP-6 were markedly increased in patients with pathogenic myopia as compared with the controls." (PMID 38203671, 2023). "The secretion of TIMP-1, MMP2, bFGF, and IGF-1, which were involved in pathological myopia, were detected with ELISA assay in ARPE-19 cells treated with 1 μg/mL of insulin for 24 or 72 h." (PMID 34001063, 2021). "The lack of a significant association between high myopia and NAFLD after metabolic adjustment suggests a different etiological pathway than insulin resistance." (PMID 40869686, 2025). "In individuals without diabetes, hyperglycemia can suppress insulin secretion, resulting in lens thickening and an anterior shift of the anterior pole, which exacerbates myopia." (PMID 39408299, 2024). "Elevated insulin levels in the bloodstream trigger the secretion of insulin-like growth factor 1 (IGF-1), which influences cell growth and differentiation, ultimately leading to axial elongation of the eyeball and the development of myopia." (PMID 39408299, 2024).
myopia (continued). "In our results the most common significant pathways/processes that could be related to myopia were axon guidance, transcription, TGF-β signaling pathway, insulin signaling, focal adhesion, MAPK signaling pathway, and EGF-EGFR signaling pathway." (PMID 36685896, 2022). "Besides, we have validated that insulin can promote the proliferation of RPE cells and the secretion of TGF-β2 in RPE cells for signal transmission and promote the occurrence of myopia." (PMID 34001063, 2021). "In summary, our study suggested that insulin acted on RPE cells as a primary signal molecule, and then increased the cell viability and promoted the secretion of pathological myopia-related factors, which was accompanied by the ultrastructure alteration, through PI3K/AKT/mTOR signaling pathway." (PMID 34001063, 2021). "Several lines of evidence support a role of insulin and/or IGF-1 in the control of eye growth, including one strong clue coming from chicken studies, in which it was shown that intravitreal injections of both peptides lead to the development of myopia." (PMID 21655358, 2011). "Furthermore, an increase in blood insulin levels is known to promote the secretion of Insulin-like growth factor 1 (IGF-1), which promotes cell growth and differentiation, leading to the axial elongation characteristic of myopia in the eye." (PMID 35333875, 2022). "Since elevated DBP would increase insulin tolerance and decrease insulin-like growth factor-1 (IGF-1) production and it was demonstrated that IGF-1 could increase myopia, a clear link between DBP and myopia can be appreciated." (PMID 18334949, 2008). "In addition, insulin enhances myopia induced by negative lens treatment." (PMID 23112573, 2012). "Although intravitreal insulin and insulin-like growth factor-1 (IGF-1) can induce myopia in chicks, it is not known if both or only one of the two signaling pathways is responsible for this effect." (PMID 23112573, 2012).
neuroendocrine tumor (33 papers, 2009 to 2025). "Hypoglycaemia associated with insulin‐secreting pancreatic neuroendocrine tumours was first reported in the early 20th century." (PMID 39740208, 2025). "Although hormonal testing did not reveal a clear cause, we suspect that glucagon secretion from a neuroendocrine tumor may have contributed to the higher preoperative insulin requirement." (PMID 40135013, 2025). "Using this antibody, we explored the correlation between GLP- 1R expression and SRS and insulin production in PanNETs and compared its expression in PanNETs with that in neuroendocrine tumors of various organs." (PMID 40281248, 2025). "It regulates circulating glucose and insulin secretion and has been identified as a therapeutic target for neuroendocrine tumors." (PMID 40713647, 2025). "Following surgical excision, histopathological analysis confirmed G1 neuroendocrine tumor, with focal cytoplasmic expression of insulin in tumor cells." (PMID 37234805, 2023). "An insulin-secreting neuroendocrine tumor was suspected based on biochemical as well as clinical data." (PMID 33807230, 2021). "Insulinomas are neuroendocrine tumours originating from the β-cells of the islets of Langerhans, which produce excess insulin and C-peptide." (PMID 24683485, 2014). "We aimed to provide an in-depth analysis with respect to three turning points in pancreas involvement in primary hyperparathyroidism (PHP): hypercalcemia-induced pancreatitis (HCa-P), MEN1 (multiple endocrine neoplasia)-related neuroendocrine tumors (NETs), and insulin resistance (IR)." (PMID 38928056, 2024). "An insulin-secreting neuroendocrine tumor was confirmed by histopathology." (PMID 33807230, 2021). "Right nephrectomy was done and it turned out to be an insulin secreting neuroendocrine tumour." (PMID 24741994, 2014). "It was considered likely that the neuroendocrine tumour was the source of the insulin secretion." (PMID 24683485, 2014). "We report a case of ectopic insulin secretion by neuroendocrine tumour (NET) of kidney." (PMID 24741994, 2014). "Herein, we describe a rare case of both insulin and ACTH secretion by a metastatic neuroendocrine tumour." (PMID 24683485, 2014). "Additional endocrinopathies, neuroendocrine tumors, other malignancies, reactivation of bladder tumors, or infections that would increase the patient’s insulin requirement were investigated, and no significant abnormality was detected." (PMID 40696585, 2025). "Whereas ATP6AP2 plays an important role in regulating insulin secretion in mouse pancreatic β cells, the expression profiles and roles of ATP6AP2 in human pancreatic endocrine cells and neuroendocrine tumor cells remain unclear." (PMID 37286698, 2023). "The patient received left-sided pancreatic resection with the histological diagnosis of a well-differentiated neuroendocrine tumor (NET) of 0.6 cm that was immunohistochemically positive for chromogranin, synaptophysin, and insulin (NET G1, Ki-67 index 1%, pT1, pN0, L0, V0, Pn0, R0, G1)." (PMID 35406570, 2022).
sleep disorder (33 papers, 2010 to 2026). A change from the patient's baseline sleeping pattern, in the hours slept and/or an alteration/dysfunction in the stages of sleep. "Prolonged sleep disorders are associated with chronically elevated cortisol levels, suppressing insulin secretion." (PMID 38641830, 2024). "Therefore, people with insulin rhythm disturbances caused by sleep disorders should adapt to their normal rhythmic activity at an appropriate time, which is consistent with our result that starchy vegetables should be eaten in the morning." (PMID 36245534, 2022). "During oral glucose tolerance test, insulin responses were attenuated, and glucagon concentrations remained consistently higher with insufficient suppression at postload time points in the sleep-disorder group." (PMID 41686553, 2026). "Sleep disorders appear to shift morning cortisol levels and sympathovagal balance, thus increasing hepatic glucogenesis and reducing insulin sensitivity." (PMID 38566084, 2024). "In conclusion, we found evidence indicating that participants with greater dietary insulin load and dietary insulin index were less likely to have sleep disorder." (PMID 37491418, 2023). "Metformin (MET), an insulin sensitizer drug, is effective in regressing MS and has been recently studied as an adjuvant agent for managing sleep disorders." (PMID 37829735, 2023). "Our aim was to determine how sleep disorders influence lipid profile and insulin sensitivity in T1D patients." (PMID 32267356, 2020). "However, these sleep disorders appear to shift morning cortisol levels and sympathovagal balance, thus increasing hepatic glucogenesis and reducing insulin sensitivity." (PMID 38566084, 2024). "Unhealthy sleep duration as well as sleep disorders may lead to muscle insulin resistance and altered muscle glucose metabolism by disturbing the circadian rhythm of skeletal muscle, resulting in decreased muscle function and grip strength." (PMID 36834111, 2023). "Consequently, it regulates insulin secretion and action, which are usually altered in concomitance with the presence of sleep disorders." (PMID 37829735, 2023). "Sleep disorders may have an association with decreased insulin sensitivity, independent of the association with adiposity." (PMID 29175807, 2018). "Sleep quality and quantity was assessed by the Sleep Disorders Questionnaire, and fasting blood was collected to quantify CRP, GGT, antioxidant micronutrients, insulin concentration, and HbA1c." (PMID 35757614, 2022). "Whether the reversed situation, improved insulin sensitivity, can be reached after restoration of the circadian rhythmicity in patients with sleep disturbances has, to the best of our knowledge, not been tested." (PMID 26204994, 2015). "Absence of some metabolic profiles (eg. insulin, HOMA index) or lack of data about sleep quality or sleep disorders could be other limitations." (PMID 35222581, 2021).